TASL (TLR adaptor interacting with endolysosomal SLC15A4)
Description:
Innate immune adapter that mediates the recruitment and activation of IRF5 downstream of endolysosomal toll-like receptors TLR7, TLR8 and TLR9. Following recruitment to endolysosome by SLC15A4 downstream of TLR7, TLR8 and TLR9, specifically recruits IRF5 transcription factor via its pLxIS motif, leading to IRF5 activation and subsequent expression of type I interferons. Plays a role in the regulation of endolysosomal pH in immune cells such as B-cells, dendritic cells and monocytes.
Synonyms: CXorf21; FLJ11577
Tractability: Antibody: UniProt places it where antibodies can reach, with high confidence.
Gene: Protein-coding gene on chromosome X (30,557,707 to 30,577,766, reverse strand). Ensembl gene ENSG00000120280.
Subcellular location: Lysosome membrane; Endosome membrane; Nucleus; Cytoplasm
Subcellular location (Human Protein Atlas): Nucleoplasm; Cytosol; Vesicles
Pathways (Reactome):
Immune System: SLC15A4:TASL-dependent IRF5 activation
Gene Ontology:
Molecular function: protein binding
Biological process: positive regulation of innate immune response; positive regulation of toll-like receptor 7 signaling pathway; positive regulation of toll-like receptor 8 signaling pathway; positive regulation of toll-like receptor 9 signaling pathway; regulation of toll-like receptor signaling pathway
Cellular component: cytoplasm; cytosol; endolysosome membrane; endosome membrane; lysosomal membrane; nucleoplasm; nucleus
Homologues: Orthologues: chimpanzee TASL (99% identical), macaque TASL (98% identical), rabbit TASL (89% identical), guinea pig TASL (87% identical), pig TASL (84% identical), mouse Tasl (83% identical), rat Tasl (83% identical), tropical clawed frog tasl (44% identical).
Diseases named in the same sentence as TASL in open-access papers:
TASL is named in the same sentence as 26 diseases in open-access papers, as found by Europe PMC text mining. Sharing a sentence is not in itself a finding about the gene and the disease. The quoted sentences say what the papers report.
systemic lupus erythematosus (17 papers, 2019 to 2026). An autoimmune multi-organ disease typically associated with vasculopathy and autoantibody production. "TASL (TLR adaptor interacting with SLC15A4 on the lysosome), encoded by the TASL (alias CXorf21) gene, is associated with systemic lupus erythematosus (SLE)." (PMID 37296415, 2023). "With the evident genetic association of the SLC15A4/TASL/IRF5 module with lupus, feeblin represents an encouraging strategy for targeting an etiological mechanism." (PMID 37863876, 2023). "For demonstration, we focus on the CXorf21 (TASL) gene, which is one of the causative candidate genes in a GWAS study for human autoimmune disease, Systemic lupus erythematosus." (PMID 36350658, 2023). "TASL is a protein associated with systemic lupus erythematosus (SLE)." (PMID 39590609, 2024). "Interestingly, SLC15A4, IRF5 and TASL are all lupus-associated genes, which strongly suggest that type I IFN production by endosomal TLRs is activated in SLE." (PMID 35812450, 2022). "We also find that deletion of TASL prevents the onset of autoimmunity in the genetically-determined B6.MRLlpr model of lupus." (PMID 41785302, 2026). "The autoimmune disease systemic lupus erythematosus (SLE) is associated with genetic variants in the X-linked gene CXORF21, which encodes the protein TASL." (PMID 41785302, 2026). "Similar to TLR7, both TLR8 and TASL are involved in the etiology of systemic lupus erythematosus (SLE), a female-biased autoimmune disease." (PMID 34858409, 2021). "Thus, PHT1 is a crucial target for therapeutic intervention in lupus and its functional and structural characterization is important to further elucidate its molecular position and in silico design of compounds that can block PHT1 activity and/or recruitment of TASL." (PMID 37709742, 2023).
autoimmune disease (12 papers, 2019 to 2026). A disorder resulting from loss of function or tissue destruction of an organ or multiple organs, arising from humoral or cellular immune responses of the individual to their own tissue constituents. "Additionally, TASL is crucial for the emergence of age-associated B cells (ABCs), a B cell population derived from the extrafollicular response that increases with age and is expanded in autoimmune disease, and the production of IgG2c antibodies." (PMID 41785302, 2026). "Together with biochemical and cellular studies, our findings provide a structural basis for drug discovery targeting SLC15A4- or TASL-related human autoimmune diseases." (PMID 37863913, 2023). "The most notable feature of X-linked genes affected by Xist perturbation is the high number of genes involved in innate immune response (TLR7, TLR8, TLR13, TASL, and CXCR3), which have been reported to be associated with or to have a causative role in different autoimmune diseases." (PMID 38701219, 2024). "Understanding how PHT1 recruits TASL at the molecular level, is therefore clinically important for the development of therapeutics against SLE and other autoimmune diseases." (PMID 37709742, 2023). "Taken together, these observations suggest that CXorf21/TASL is a strong candidate gene in SLE, for which enhanced dosage in female immune cells due to XCI escape may contribute to the gender bias observed in some autoimmune diseases such as SLE." (PMID 33498655, 2021).
Autoimmunity (3 papers, 2024 to 2026). The occurrence of an immune reaction against the organism's own cells or tissues. "Due to the predominance of autoimmune females, the field has tended to view sex differences through a pathological lens, that is, autoimmunity, emphasizing how proteins like TASL contribute to the production of deleterious agents." (PMID 38184662, 2024). "In this study, we show that TASL and its newly identified paralogue TASL2 play a central role in endosomal TLR7/9-induced responses in vivo, affecting both antiviral immune and autoimmune SLE models." (PMID 39856058, 2025).
astrocytomas (1 paper, 2023). "The expression levels of TASL were higher in isocitrate dehydrogenase (IDH)-wildtype (IDH-WT) than that in IDH-mutant (IDH-Mut) patients, in 1p/19q non-co-deletion than that in 1p/19q co-deletion patients, and in astrocytomas (A) than that in oligoastrocytomas (OA) and oligodendrogliomas (OD)." (PMID 37296415, 2023).
COVID-19 (1 paper, 2021). A disease caused by infection with severe acute respiratory syndrome coronavirus 2. "TASL has not been associated with COVID-19 directly, but indirectly via its adaptor function in the TLR7-mediated IFN pathway." (PMID 34858409, 2021).
glioma (1 paper, 2023). A benign or malignant brain and spinal cord tumor that arises from glial cells (astrocytes, oligodendrocytes, ependymal cells). "We also investigated the association of TASL protein expression with age, histological types, and clinical molecular indicators such as Ki-67 in glioma patients." (PMID 37296415, 2023). "We found that in gliomas, the expression of TASL increased with increasing WHO grade of patients (P < 0.01)." (PMID 37296415, 2023). "High TASL expression is an independent poor prognostic factor for immune “cold” tumor Low-Grade Glioma (LGG) but an opposite factor for “hot” tumors Lung Adenocarcinoma (LUAD) and Skin Cutaneous Melanoma (SKCM)." (PMID 37296415, 2023). "The results of our clinical cohort study are consistent with those in public databases, suggesting that TASL expression in gliomas is positively correlated with the malignancy of the tumor." (PMID 37296415, 2023). "Several studies have found that increased TLR7 and TLR9 expression in glioma tissues is related to poorer prognosis, while TASL is located downstream of TLR7-9, which indirectly supports the conclusion that high TASL expression is related to poor prognosis of LGG." (PMID 37296415, 2023). "Finally, we tested TASL expression in human glioma cell lines and tissue samples and analyzed its correlation with clinicopathological parameters." (PMID 37296415, 2023). "High TASL expression is a potential biomarker for the positive response to immunotherapy in cancers such as SKCM and was also experimentally confirmed to be positively associated with adverse clinicopathological features of gliomas." (PMID 37296415, 2023). "In addition, we tested the expression of TASL protein in human glioma tissues by IHC." (PMID 37296415, 2023). "In our study, TASL has been inferred antitumor effect in SKCM and LUAD, but has a tumor-promoting effect in glioma, which may be related to the cellular composition of tumor tissues in different tumor types." (PMID 37296415, 2023).
viral infection (1 paper, 2025). "Altogether, these data revealed that the SLC15A4-TASL axis is critical to control chronic viral infection and that the two TASL paralogues are functionally redundant to restrict LCMV in vivo, as only TASLDKO show persistent viral titre as in feeble mice." (PMID 39856058, 2025).
tumor (2 papers, 2023). "The association with the TASL expression and immune-stimulating microenvironment in the “cold” tumor LGG, “hot” tumors LUAD and SKCM was revealed in this study." (PMID 37296415, 2023). "TASL may affect tumor immune infiltration by mediating tumor-infiltrating lymphocytes and tumor-associated macrophages." (PMID 37296415, 2023). "Since overexpression of immune checkpoint genes tends to be positively correlated with high response rates to immunotherapy, our analysis implied that TASL expression may be associated with tumor immunotherapy response." (PMID 37296415, 2023). "TASL mRNA is significantly differentially expressed in tumor and normal groups in 20 of the 33 kinds of cancers (P < 0.01)." (PMID 37296415, 2023). "Except for ACC, OV, PRAD, STAD, and TGCT, there were significant differences in TASL expression between other types of tumor and normal tissues (P < 0.05)." (PMID 37296415, 2023). "We first analyzed TASL mRNA expression in tumor and normal samples of 33 cancer types and revealed a tissue-dependent role for TASL in tumor development." (PMID 37296415, 2023). "To further verify the differences in TASL expression between tumor and normal samples, we compared microarray data for 20 types of cancers in the GEO database." (PMID 37296415, 2023). "We found that high TASL expression may be an independent poor prognostic factor for the “cold” tumor LGG and an independent favorable prognostic factor for the “hot” tumors LUAD and SKCM." (PMID 37296415, 2023). "TASL has both suppressive and promotive effects on human cancer, and its high expression could be an independent poor prognostic factor for immune “cold” tumor LGG and a favorable prognostic factor for immune “hot” tumors LUAD and SKCM." (PMID 37296415, 2023). "Our results revealed that TASL may affect the occurrence and development of cancer by regulating immune and metabolic pathways, and TASL of the TLR pathway may be involved to some extent in the cross-talk between tumor immune and metabolic pathways." (PMID 37296415, 2023). "TASL might play a role in promoting cancer in tumor cells, while LUAD and SKCM were immune “hot” tumors, the extensive activation of TASL in immune cells leads to a better prognosis in patients with high TASL expression." (PMID 37296415, 2023). "Since a high level of immune infiltration is a favorable condition affecting tumor response to immunotherapy, we explored whether high TASL expression could predict a high level of immune infiltration in tumors." (PMID 37296415, 2023). "The K-M curves showed that the “cold” tumor LGG patients with higher TASL expression tended to have an ominous prognosis (P < 0.01), while the “hot” tumors LUAD (P < 0.001) and SKCM (P < 0.001) patients with higher TASL expression tended to have a better prognosis." (PMID 37296415, 2023). "Next, we analyzed the correlation between TASL expression and the content of immunostimulatory and immunosuppressive cells in the “cold” tumor LGG, the “hot” tumors LUAD and SKCM to further explore the relationship between TASL expression and various TIIC infiltration patterns." (PMID 37296415, 2023). "Further basic studies focusing on TASL expression and tumor immunotherapy are urgently needed." (PMID 37296415, 2023). "In the “hot” tumor SKCM, TASL expression was positively correlated with all 20 types of TIICs, and the greatest correlation was found with T cells (R = 0.790, P < 0.001)." (PMID 37296415, 2023). "These implied that TASL, a key factor in the TLR pathway, regulates opposite immune functions in the “cold” tumor LGG and the “hot” tumors LUAD and SKCM." (PMID 37296415, 2023). "In the “cold” tumor LGG, TASL expression was significantly and positively correlated with the content of immunosuppressive Th2 cells (R = 0.350, P < 0.001) and M2 macrophages (R = 0.280, P < 0.001), and less correlated with the content of immunostimulatory Th1 cells (R = 0.170, P < 0.001)." (PMID 37296415, 2023).
tumor (continued). "In the “hot” tumor, LUAD, TASL expression most correlated with macrophages (R = 0.641, P < 0.001)." (PMID 37296415, 2023). "Conversely, TASL may enhance the ability of immune cells in the “hot” tumors LUAD and SKCM to kill tumor cells by recruiting Th1 cells in LUAD, CD8+ T cells in SKCM, and inducing the conversion of M2 macrophages to M1 macrophages in SKCM." (PMID 37296415, 2023). "In addition, this study presents for the first time that high TASL expression is also a potential biomarker for the positive response to immunotherapy in various cancer types such as SKCM, which provides new ideas for current research in tumor immunotherapy." (PMID 37296415, 2023). "But we do not know whether TASL is involved in tumor development and immunotherapy response prediction." (PMID 37296415, 2023). "However, whether TASL is involved in tumor development and immunotherapy response prediction has not been reported." (PMID 37296415, 2023). "In addition, in “cold” tumor LGG, we also observed a significant negative correlation between TASL expression and CD56bright NK cells and pDCs." (PMID 37296415, 2023).
cancer (1 paper, 2023). A tumor composed of atypical neoplastic, often pleomorphic cells that invade other tissues. "Therefore, even with the important results of our correlation analysis, the mechanisms underlying the role of TASL in TME in different cancer types deserve further exploration." (PMID 37296415, 2023). "We found that TASL expression was highly positively correlated with these immune signatures in 20 cancer types, in particular, the correlation between TIL and TASL expression was most significant." (PMID 37296415, 2023). "We observed that TASL expression was strongly positively correlated with immune checkpoint genes in 18 cancer types, except LAML and THYM, which were weakly positively correlated (P < 0.001)." (PMID 37296415, 2023). "High TASL expression is a potential biomarker for the positive response to immunotherapy in certain cancer types such as SKCM." (PMID 37296415, 2023). "The results showed that several immune-related pathways such as “intestinal immune network for IgA production”, “Toll-like receptor signaling pathway”, etc., were significantly upregulated in the TASL high expression group in most cancer types." (PMID 37296415, 2023). "TCGA and GTEx were used to yield transcriptional, genetic, and epigenetic levels of TASL in 33 cancer types." (PMID 37296415, 2023). "The results showed that except for the G3 grade of LGG, T3 + T4, and M1 stage of LUAD, TASL expression had good predictive power for OS in patients with the three types of cancers in other clinical grades or stages (P < 0.05)." (PMID 37296415, 2023). "COX regression analysis was to investigate the relationship between TASL expression and OS in patients with various cancers." (PMID 37296415, 2023). "Firstly, we divided patients into two groups, “high” and “low”, based on the median value of TASL expression in the TCGA's 20 cancer cohorts, and then performed GSEA for KEGG pathways." (PMID 37296415, 2023). "TASL expression was found to be significantly and positively correlated with the content of most TIICs in the three cancer types." (PMID 37296415, 2023). "In our study, differential enrichment of several immune, metabolic, and cancer-related pathways was observed between high and low TASL expression groups." (PMID 37296415, 2023). "TASL was significantly differentially expressed in different cancer types, with extensive heterogeneity at the transcriptional, genetic, and epigenetic levels." (PMID 37296415, 2023). "In conclusion, we found extensive heterogeneity in TASL of human cancers at the transcriptional, genetic and epigenetic levels." (PMID 37296415, 2023). "TASL upregulates some immune-related pathways in most cancer types." (PMID 37296415, 2023). "This is the first study to look into the impact of TASL expression on cancer survival." (PMID 37296415, 2023). "Given the good predictive efficacy of TASL expression for immune infiltration, we further investigated the correlation between TASL expression and TMB, MSI, and immune checkpoint gene expression (calculated by ssGSEA) of 20 cancer types in TCGA." (PMID 37296415, 2023). "We also performed an analysis of the correlation between mRNA expression and DNA methylation of TASL and found a negative correlation between the two in 30 cancer types including KIRP, LAML, and LUAD (FDR < 0.05)." (PMID 37296415, 2023). "However, there has been no study on the role of TASL in different cancers so far." (PMID 37296415, 2023).
skin disorder (1 paper, 2024). Any deviation from the normal structure or function of the skin or subcutaneous tissue that is manifested by a characteristic set of symptoms and signs. "Still, this study provides a foundation for understanding the multifaceted involvement of TASL in keratinocyte function and suggests its broader implications in therapeutic interventions beyond skin disorders." (PMID 38744928, 2024).
TASL also shares sentences with these, for which no sentence is quoted: Sjögren’s syndrome (4 papers); breast carcinoma (1); glioblastoma multiform (1); infection (1); Klinefelter syndrome (1); lung adenocarcinoma (1); lymphoma (1); melanoma (1); metastatic tumors (1); oligoastrocytoma (1); oligodendroglioma (1); Primary amenorrhea (1); psoriasis (1); rheumatoid arthritis (1); Skin Cutaneous Melanoma (1); thymoma (1).